BDNF (brain derived neurotrophic factor)
Diseases named in the same sentence as BDNF in open-access papers (continued):
Sharing a sentence is not in itself a finding about the gene and the disease.
cardiovascular disease (85 papers, 2008 to 2026). "BDNF represents one of the most common biomarkers of a healthy brain and lower serum BDNF levels are associated with a higher risk of depressive symptoms in women with cardiovascular disease." (PMID 40519780, 2025). "In another study, it was found that individuals with T2DM and the Val/Val genotype of the BDNF (brain-derived neurotropic factor) gene were more likely to be at risk of cardiovascular disease, compared to subjects carrying Met-alleles." (PMID 38474713, 2024). "The 2015 Framingham Heart Study suggests that high BDNF levels are associated with a lower risk of cardiovascular disease and mortality." (PMID 38137853, 2023). "Such a suggestion is in line with previous human studies that have linked reduced serum or plasma BDNF levels to a higher incidence of various cardiovascular diseases." (PMID 38152248, 2023). "Several studies reported the association between the rs6265 polymorphism, an exonic variant in the BDNF gene, and both neuropsychiatric disorders and cardiovascular disease." (PMID 36782254, 2023). "This work aimed to evaluate the overall evidence that has emerged about the association between BDNF and cardiovascular disease." (PMID 38137853, 2023). "Previous studies indicated that a low circulating BDNF (brain-derived neurotrophic factor) level was linked with a poor prognosis in cardiovascular diseases (Yılmaz, 2019)." (PMID 37228653, 2023). "Consistently, a prospective analysis in a large community-based cohort demonstrating that higher serum BDNF levels are associated with a decreased risk for future cardiovascular disease events and mortality." (PMID 35906216, 2022). "Brain-derived neurotrophic factor (BDNF) belongs to the “neurotrophin” family of growth factors, and it has recently been associated to cardiovascular disease (CVD)." (PMID 34580389, 2021). "Very few other pediatric studies have investigated relations between BDNF genotype, energy intake, and cardiovascular disease risk factors." (PMID 34867148, 2021). "In a human study, low levels of BDNF were associated with cardiovascular diseases and cardiac remodeling." (PMID 34210092, 2021). "Recent evidence suggests that BDNF has adverse subclinical cardiac remodeling in participants with cardiovascular disease risk factors." (PMID 33004884, 2020). "It is suggested that the lower levels of BDNF in aging individuals make them more susceptible to suffering from cardiovascular disorders." (PMID 33343231, 2020). "Decreased plasma BDNF levels have been reported in patients with or at risk for cardiovascular disease." (PMID 29409455, 2018). "In contrast, high BDNF levels in a large community-based cohort were also prospectively associated with a decreased risk of cardiovascular disease and mortality." (PMID 29409455, 2018). "Higher plasma BDNF levels were associated with risk factors for cardiovascular disease including elevated diastolic blood pressure and triglycerides in men and elevated diastolic blood pressure, total and LDL cholesterol, BMI and fat mass in women." (PMID 20404913, 2010). "However, plasma BDNF levels have been associated with risk factors for cardiovascular disease, including blood pressure, triglycerides, total cholesterol, and BMI." (PMID 36970903, 2023). "Further support for the implication of the nervous system in SCD was the statistical significance that we found in a variant (rs988748) in the BDNF gene through the case–control comparison; indeed, the neurotrophic factor encoded by this gene is highly related to cardiovascular disease development." (PMID 37372445, 2023). "BDNF represents an emerging target for cardiovascular research due to its diverse effects of heart centric homeostasis with alterations in expression in this growth factor implicated in a wide variety of cardiovascular diseases." (PMID 34543287, 2021).
cardiovascular disease (continued). "As a result, food consumption may influence the relationship between BDNF polymorphism and cardiovascular disease indicators via BDNF expression and serum protein modulation." (PMID 34580389, 2021). "However, further studies with intervention treatments are needed to determine the causal relationship between the reduction in the serum BDNF level after glucose intake and cardiovascular disease." (PMID 32679912, 2020). "We previously reported that a lower AUC of BDNF was associated with higher central pulse pressure after oral glucose intake and that poor postprandial vascular performance might be associated with cardiovascular disease." (PMID 32679912, 2020). "In this notion, decreased expression of BDNF in the preterm gestation might lead to abnormal fetal growth that may increase the risk of cardiovascular diseases and metabolic abnormalities in the postnatal life of children born preterm." (PMID 32075190, 2020). "Finally, higher plasma BDNF levels seem to be associated with risk factors for cardiovascular disease including elevated diastolic blood pressure, higher cholesterol and higher BMI." (PMID 26011424, 2015). "It is possible that BDNF contributes to the pathophysiology of cardiovascular disease, or elevated plasma BDNF may represent a compensatory response to an underlying disease processes." (PMID 20404913, 2010). "Therefore, our findings supported the positive association between BDNF levels and BP, which is in accordance with the previous reports that suggested functions for BDNF in cardiovascular homeostasis and that increased BDNF levels were associated with increased risk of cardiovascular disease." (PMID 37007871, 2023). "Moreover, BDNF itself can directly impact the risk of cardiovascular disorders (CVD)." (PMID 33343231, 2020). "This suggests that altered BDNF metabolism and trafficking and/or altered regulation of contractility genes plays a significant role in the phenotype and may represent a novel role for this polymorphism as a modulator of cardiovascular disease." (PMID 33050457, 2020). "Hence, the directionality and causality between BDNF and cardiovascular disease is still undetermined and may be related to signal cross-talk." (PMID 31659205, 2019). "The findings from one study favors Met carriers, suggesting that Met allele favorably interacts with cognitive changes associated with the cardiovascular disease or that cardiovascular diseases may have affected circulating levels of BDNF, given that BDNF is permeable to the blood–brain barrier." (PMID 29858545, 2018). "Recent evidence suggests a potential role for brain-derived neurotrophic factor (BDNF) in the pathophysiology of cardiovascular disease, including HF." (PMID 40507974, 2025). "In cardiovascular diseases, BDNF is involved in cardioprotective and cardiac rehabilitation processes." (PMID 38707889, 2024). "When BDNF and its receptor tropomyosin receptor kinase B are missing in the signaling pathway, brain and cardiovascular diseases are also more likely to occur." (PMID 39648800, 2024). "To date, several studies and reviews have shown that altered BDNF levels are common in patients with cardiovascular diseases and that specific BDNF genotypes (e.g., Val66Met) are common in patients at higher risk for cardiovascular disease." (PMID 38137853, 2023). "In recent decades, brain-derived neurotrophic factor (BDNF) has emerged as a strategic molecule involved in both brain and cardiovascular disease (CVD)." (PMID 38137853, 2023). "The results regarding BDNF genotype were variable in relation to race and ethnicity and cardiovascular disease." (PMID 38137853, 2023). "Nevertheless, much work remains to be carried out in current research to investigate how BDNF is modulated in different cardiovascular diseases and in different populations." (PMID 38137853, 2023).
cardiovascular disease (continued). "While several studies have ascertained the protective effect of BDNF on cardiovascular disease and mortality, relatively few studies have explored the relationship between BDNF and CKD, especially in patients with CAD." (PMID 35800175, 2022). "BDNF has extensive roles by binding to tropomyosin-related kinase receptor B (TrkB), and the BDNF/TrkB pathway is found closely related to the outcome of cardiovascular diseases, including HF." (PMID 35439934, 2022). "The significant correlation between diastolic pressure and BDNF in both males and females strongly suggests that plasma BDNF is important for cardiovascular disease." (PMID 35626286, 2022). "Our studies suggest signaling pathways related to BDNF within subregions of both the rostral ventrolateral medulla and its rostral extension contribute to cardiovascular disease and premature death related to a sedentary lifestyle." (PMID 34721079, 2021). "In humans, circulating BDNF has been correlated with a variety of pathological conditions, including some cardiovascular disorders." (PMID 34210092, 2021). "Thus, low BDNF accumulation after glucose intake might be associated with cardiovascular disease." (PMID 32679912, 2020). "BDNF has a multifaceted role from its neurotrophic activity to inflammation, metabolism, and cardiovascular diseases." (PMID 32942585, 2020). "Overall, previous research suggests a link between BDNF, cardiac function and cardiovascular disease." (PMID 31659205, 2019). "Recent studies have underlined the possible implication of neurotrophins and specifically Brain Derived Neurotrophic Factor (BDNF) in cardiovascular diseases and myocardial injury: two situations in which inflammation is involved." (PMID 23675091, 2008). "Cardiovascular disorders such as ischemia and necrosis are connected with high levels of oxidative stress, and BDNF itself shows capacities of activation of oxidative enzymes like NAD(P)H oxidases." (PMID 23675091, 2008). "Understanding the impact of altered BDNF levels in hypertensive patients with DMM on various factors related to cardiovascular diseases and brain functions might be explored." (PMID 39916293, 2025). "However, BDNF levels decrease in individuals with cardiovascular diseases or chronic mental disorders." (PMID 39648800, 2024). "MiR-132 may contribute to MDD and cardiovascular disease co-occurrence, with suppression increasing BDNF levels." (PMID 39457478, 2024). "Numerous studies have indicated a significant role for BDNF in cardiovascular diseases." (PMID 39648800, 2024). "BDNF, synthesized not only in neurons but also in immune cells, adipocytes, endothelial cells, and monocytes, plays a multifaceted role from its neurotrophic activity to its involvement in inflammation, metabolism, and cardiovascular diseases." (PMID 38673018, 2024). "Therefore, this study retrospectively investigated the effects of baseline serum BDNF levels on the CR-induced exercise capacity improvement in patients with cardiovascular disease (CVD)." (PMID 38319936, 2024). "BDNF is also a key regulatory factor of cardiovascular disease." (PMID 35906216, 2022). "Brain-derived neurotrophic factor (BDNF) may be a new important predictor of cardiovascular disease." (PMID 35906216, 2022). "Additionally, BDNF has a multifaceted role from its neurotrophic activity to inflammation, metabolism, and cardiovascular diseases." (PMID 32942585, 2020). "Furthermore, we found that BDNF protein levels were significantly correlated with the levels of CK-MBm and Myo, which have been widely used in the diagnosis of cardiovascular diseases." (PMID 31682178, 2019). "BDNF plays a role in the progression of human cardiovascular disease." (PMID 31659205, 2019). "Alterations in BDNF signaling are related to the development of cardiovascular disease." (PMID 31659205, 2019). "First, we did not directly assess the mechanism underlying the high BDNF AUC index in cardiovascular disease." (PMID 27787389, 2016).
cardiovascular disease (continued). "On the other hand, a longitudinal study including a large community-based cohort detected higher serum BDNF levels significantly associated with lower risk of cardiovascular diseases and mortality, independent of markers of low-grade inflammation, BMI, physical activity, and depression." (PMID 30542302, 2018). "We found that bioavailable testosterone levels were directly correlated to plasma BDNF levels in males, and the opposite occurred for SHBG, indicating that plasma BDNF could play a role in the pathogenesis of metabolic and cardiovascular disorders in male hypogonadism." (PMID 20404913, 2010). "Therefore, BDNF may be a bridge between psychiatric disorders and cardiovascular disease." (PMID 32679912, 2020). "Brain-derived neurotrophic factor (BDNF) has been shown to have protective effects against cardiovascular diseases and death through neural and non-neural pathways via tropomyosin-related kinase B signaling." (PMID 28575038, 2017).
infection (82 papers, 2011 to 2025). The state of being infected such as from the introduction of a foreign agent such as serum, vaccine, antigenic substance or organism. "Studies in rat models have manifested that infection can cause alterations in the expression of BDNF." (PMID 37365274, 2023). "We have investigated the role of the BDNF-TrkB signaling in the development of seizures in a model of TMEV infection-associated limbic epilepsy." (PMID 35874836, 2022). "Further studies are warranted to test the strategies for modulating the BDNF-TrkB signaling and their impact on chloride homeostasis and occurrence of infection-associated seizures." (PMID 35874836, 2022). "However, the BDNF/adiponectin ratio was significantly associated with the worst prognosis during the infection." (PMID 37408184, 2023). "The infection of A. cantonensis cause eosinophilic meningoencephalitis, and a large amount of eosinophil infiltration may also increase the expression of BDNF." (PMID 35414007, 2022). "Moreover, BDNF helps to protect neurons from damage caused by infection or injury and participates in neuronal growth and maintenance and in different aspects of activity-dependent synaptic physiology by acting across different spatial and temporal domains." (PMID 32397504, 2020). "Moreover, following the infection with the BDNF-encoding lentivirual vectors, the vast majority of cultured MSCs were positive for BDNF protein." (PMID 30759764, 2019). "BDNF helps to protect neurons from damage caused by infection or injury." (PMID 28286417, 2017). "Direct applications of BDNF, e.g., via integrated drug-delivering cannula, elevate the surgical risks, as well as the probability of infections." (PMID 40763163, 2025). "As for the involvement of NGF and BDNF in long-lasting symptomatology linked to SARS-CoV-2 contagion, few studies have taken into consideration the cognitive impairment observed after infection." (PMID 39596862, 2024). "Infection with this virus also results in a decrease in brain-derived neurotrophic factor (BDNF) and glial cell-derived neurotrophic factor (GDNF), which encode key factors essential for maintaining neural plasticity." (PMID 39840010, 2024). "A previous study on respiratory syncytial virus-infected mice showed BDNF elevation in the lung during the period of the infection." (PMID 39403060, 2024). "This is consistent with BDNF being an important messenger between neurons and glia; particularly during times of infection, injury or cellular stress." (PMID 37404293, 2023). "By using RT-PCR, we observed the down-regulation of BDNF in mouse lungs during the infection with IAV." (PMID 38005876, 2023). "The increase in BDNF expression in CASK KO CG cells was attenuated by reexpression of CASK by lentiviral infection in CASK KO CG cells." (PMID 37190086, 2023). "Our results showed that CUR treatment slightly increased BDNF levels in the frontal cortex from day 21 post-infection." (PMID 35216083, 2022). "We found a significant increase in the protein levels of BDNF in hippocampus after TMEV infection that was coincident with seizure activity." (PMID 35874836, 2022). "The present study was performed to question whether BDNF-TrkB signaling contributes to hyperexcitability by altering the activity of cation-chloride cotransporters in a model of Theiler’s murine encephalomyelitis virus (TMEV) infection-associated acquired limbic epilepsy." (PMID 35874836, 2022). "At the same time, the infection induced the mRNA expression for brain-derived neurotrophic factor (BDNF) and neuronal growth factor (NGF), which facilitate actions such as synapses plasticity and formation." (PMID 35154065, 2021). "In our murine model of TB, we observed a decrease in BDNF after 60 and 120 days of infection in hypothalamus, hippocampus and cerebellum." (PMID 33322180, 2020).